FOXA1 (forkhead box A1)
Diseases named in the same sentence as FOXA1 in open-access papers (continued):
Sharing a sentence is not in itself a finding about the gene and the disease.
breast carcinoma (continued). "We observed that the top five strongest TF co-occupancy pairs associated with breast cancer risk were FOXA1 + E2F1, FOXA1 + NR2F2, FOXA1 + ESR1, FOXA1 + SIN3, and FOXA1 + TCF12." (PMID 34518541, 2021). "Prior studies indicate that FOXA1 functions in conjunction with ER to influence enhancer activity and promote pro-metastatic transcriptional programming in breast cancer cell lines." (PMID 34922480, 2021). "FOXA1 high expression connects with good prognosis in breast cancer by relieving the epithelial-to-mesenchymal transition process and inhibiting migration, invasion, and metastasis." (PMID 33336077, 2021). "FOXA1 positively regulates gene expression by altering the gene methylation status in human breast cancer Michigan Cancer Foundation-7 (MCF-7) cells." (PMID 34512726, 2021). "FOXA1, in turn, stimulates transcription of HER2-regulated genes in a feed-forward loop, revealing crosstalk between receptor tyrosine kinases, such as HER2, with FOXA1 in breast cancers that lack ER expression." (PMID 34680352, 2021). "Of note, while FOXA1 is selectively upregulated in luminal breast cancers, a significant proportion of TNBCs (~30%) also express FOXA1." (PMID 34680352, 2021). "The associations of breast cancer risk for ESR1-E2F1, ESR1-TCF12, TCF12-TLE3, and SIN3-TLE3 pairs were significantly stronger in loci also occupied by FOXA1 (P < 1 ×10−5)." (PMID 34518541, 2021). "FOXA1 is a protein that is highly expressed in a majority of breast cancers and its binding to DNA helps define which genes are regulated by nuclear receptors." (PMID 34680352, 2021). "FOXA1 modulation of anchorage independence and drug sensitivity supports a role in orchestrating programs making breast cancer cells more aggressive." (PMID 33417085, 2021). "There are several lines of evidence that support pharmacological inhibition of FOXA1 in breast cancer." (PMID 34680352, 2021). "Together, these studies suggest a positive role for FOXA1 in ESR1 up-regulation in ER+ breast cancer cells, with possible cross-talk with several FOX factors." (PMID 34831189, 2021). "While the pioneering function of FOXA1 in estrogen-driven breast cancers has been extensively reported, two studies directly challenge this paradigm." (PMID 34680352, 2021). "Receptors for androgens, glucocorticoids, and progesterone are also found in the majority of breast cancers, and their functions are also impacted by FOXA1." (PMID 34680352, 2021). "Although we do not currently know the genes downstream from FOXA1 which regulate multidrug resistance, our data clearly supports a role of FOXA1 in the regulation of genes controlling response to doxorubicin and paclitaxel in breast cancer cell models." (PMID 33417085, 2021). "FOXA1 is expressed in all luminal breast cancer cell lines, all ER-positive tumors, and about half of ER-negative tumors." (PMID 33417085, 2021). "In conclusion, this manuscript describes a novel pathway involving JAM-A-dependent expressional regulation of HER3 in breast cancer settings by modulating first β-catenin localization and subsequently FOXA1 expression." (PMID 33669586, 2021). "FOXA1 also has an NR-independent function in HER2-enriched breast cancers, where it is expressed in ~70% of this tumor type." (PMID 34680352, 2021). "Given the well-established role of FOXA1 in mediating AR transcriptional programs in prostate cancer, it is logical to predict that these two proteins also cooperate in molecular apocrine breast cancer to promote AR activation and target gene expression." (PMID 34680352, 2021). "FOXA1 is predominantly considered a pioneer factor for ER from studies in ER+ breast cancer as well as the androgen receptor (AR) in prostate cancer, promoting chromatin accessibility for these TFs28,34,45." (PMID 33980863, 2021).
breast carcinoma (continued). "In fact, the AR-binding profile in this cell line is more similar to the breast cancer ER-cistrome than AR-binding events in prostate cancer, indicating that FOXA1 directs AR binding to ER consensus sites." (PMID 34680352, 2021). "It has been reported that FOXA1 cooperates with estrogen receptor-α (ESRa) to regulate chromatin accessibility in breast cancer." (PMID 34202157, 2021). "FOXA1 dysregulation is an essential event in breast cancer progression and subtype characterization." (PMID 33861732, 2021). "O-GlcNAcylation of FOXA1 reduces protein stability, leading to the downregulation of the pro-apoptotic Bim protein, thereby inhibiting apoptosis in breast cancer cells." (PMID 33916244, 2021). "More recently, it has been demonstrated that FOXA1 upregulation in ER positive breast cancer cells drives global enhancer reprogramming to activate prometastatic transcriptional programs." (PMID 34616687, 2021). "Taken together, these data confirm that we have successfully edited the FOXA1 protein sequence by site‐directed mutagenesis of the endogenous loci of FOXA1 in breast cancer cells." (PMID 33666335, 2021). "Here we present data indicating that FOXA1 regulates doxorubicin and paclitaxel resistance in breast cancer cells." (PMID 33417085, 2021). "A comparison of PR cistromes between normal breast and breast cancer cell lines uncovered an enrichment of FOXA1 consensus elements near PR binding sites in breast cancer compared to normal breast." (PMID 34680352, 2021). "The pioneering functions of FOXA1 and nuclear receptor (NR) transcriptional programs are tightly coupled in breast cancer." (PMID 34680352, 2021). "Over the past two decades, FOXA1 has been shown to play diverse roles in organ development as well as in several diseases, including breast cancer." (PMID 34680352, 2021). "In this review, we provide an update on the role of FOXA1 in controlling NR function in breast cancer and identify areas requiring additional focus to delineate the full spectrum of FOXA1 functions in this disease." (PMID 34680352, 2021). "Among the top hits, we identify a cancer-testis unitary pseudogene, MGAT4EP, that is predominantly localized in the nucleus and interacts with FOXA1, a key regulator in luminal A breast cancer." (PMID 34425866, 2021). "Despite these data and the established role of FOXA1 in governing ER and AR transcriptional programs, little is known regarding the impact of FOXA1 on GR target genes in this breast cancer subtype." (PMID 34680352, 2021). "This review discusses the current literature on how FOXA1 controls gene activity, cell biology, and the response of breast cancers to hormone therapies." (PMID 34680352, 2021). "Together, this work revealed that FOXA1 is essential for activation of chromosome-specific, ER-dependent transcriptional programs in luminal breast cancer." (PMID 34680352, 2021). "Most GR binding events (69%) overlap with FOXA1-bound loci in luminal breast cancer cells devoid of glucocorticoids." (PMID 34680352, 2021). "By characterizing multiple therapy-resistant breast cancer models, previous studies have shown that high FOXA1 activity can reprogram ERα-dependent transcriptome to promote endocrine-resistant cell growth and invasiveness." (PMID 34616687, 2021). "Herein, we review what is known regarding FOXA1 regulation of NR function in breast cancer in the context of cell identity, endocrine resistance, and NR crosstalk in breast cancer progression and treatment." (PMID 34680352, 2021). "Large-scale gene expression studies of breast cancer cell lines and primary tumor tissue were instrumental in identifying the selective upregulation of FOXA1 in luminal breast cancers and its strong correlation with ESR1 expression." (PMID 34680352, 2021). "Next, we determined how an experimental variation in FOXA1 expression levels would affect the sensitivity of breast cancer cells to drugs commonly used in cancer chemotherapy." (PMID 33417085, 2021).
breast carcinoma (continued). "The most important TFs for breast cancer, such as FOXA1 and ESR1, are among the most significant results from the mixed model but less evident in the results from the LD score regression." (PMID 34518541, 2021). "As our study had led us to a linear mechanism connecting JAM-A, β-catenin, FOXA1 and HER3 (in that order), we analyzed expressional associations between those proteins in the 144-patient breast cancer TMA." (PMID 33669586, 2021). "The combinations of TRs associated with the transcriptional activator FOXA1 are studied here, in the MCF7 breast cancer cell line." (PMID 34988437, 2021). "For our studies, we sought to specifically modify the pioneer transcription factor FOXA1 in the Luminal A breast cancer cell line MCF‐7." (PMID 33666335, 2021). "Taken together, the current work revealed that menin interacts both with GATA3 and FOXA1 in ER + breast cancer cells." (PMID 34561764, 2021). "Beyond facilitation of hormone receptor signaling, FOXA1 overexpression has been shown to contribute to tamoxifen insensitivity of breast cancer cells in a mechanism that involves induction of interleukin-8." (PMID 34831189, 2021). "Other studies based upon ChIP-Seq and ChIP-PCR in breast cancer cells have indicated that FOXA1 binds to the HER3 gene." (PMID 33669586, 2021). "In tamoxifen-sensitive breast cancer cells, tamoxifen-ER binding events significantly overlap (93%) with those of estrogen-bound ER, and likewise, tamoxifen-bound ER requires FOXA1 for chromatin engagement and inhibitory action." (PMID 34680352, 2021). "Based on our findings, we propose that FOXA1 is key to HER2+ breast cancer cell identity and adaptive reprogramming." (PMID 33980863, 2021). "Taken together, our findings are consistent with a linear model in which high expression of JAM-A influences nuclear β-catenin levels, in turn increasing FOXA1 expression which then promotes HER3 expression in breast cancer settings." (PMID 33669586, 2021). "In ER+ breast cancer, pioneer TFs like FOXA1, GATA3, PBX1, and AP-2γ bind specific DNA target sequences in condensed chromatin and facilitate ERα chromatin binding in response to E2 stimulation." (PMID 33741974, 2021). "Like ER, androgen receptor (AR) is expressed in the majority (~85%) of breast cancers and is positively correlated with FOXA1 expression, yet its role in breast cancer is less understood." (PMID 34680352, 2021). "FOXA1 overexpression comprises a major proliferation and survival signal for luminal type A breast cancer, which has been attributed to the amplification of FOXA1 in around 6% of primary tumors and 10% of metastatic ER+ (estrogen receptor positive) tumors." (PMID 35011637, 2021). "Here we describe the generation of breast cancer cell models in which FOXA1 expression has been modulated either by expression of hairpins targeting FOXA1 mRNA or overexpression plasmids." (PMID 33417085, 2021). "As a whole, these studies revealed that the function of FOXA1 extends beyond its canonical role of modulating ER activity in breast cancer." (PMID 34680352, 2021). "In this study we have experimentally modulated FOXA1 levels in breast cancer cell models and determined its role in drug resistance and tumor formation in vitro." (PMID 33417085, 2021). "In order to study how breast cancer cells respond to experimental FOXA1 modulation, we first determined FOXA1 expression levels in a small panel of breast cancer cell lines." (PMID 33417085, 2021). "For example, steroid receptor activation in breast cancer cell lines induces FOXA1 recruitment to sites with degenerate FOXA1-binding motifs, exemplifying heterogeneity in FOXA target site engagement." (PMID 34789735, 2021). "We find that, by analyzing genetic variations of TF-DNA bindings, the interaction of FOXA1 with co-factors such as ESR1 and E2F1, and the interaction of TFs with chromatin features (i.e., enhancers) play a key role in breast cancer susceptibility." (PMID 34518541, 2021).
breast carcinoma (continued). "Combined, these studies nominate PR as a direct transcriptional modulator of ER function and breast cancer outcomes, likely in a FOXA1-independent manner." (PMID 34680352, 2021). "The shared cell lineage of HER2+ breast cancer with other luminal breast cancers prompted deeper investigation into a potential role for FOXA1 in HER2+/ER− breast cancer." (PMID 33980863, 2021). "FOXA1, GATA3 and SPDEF are key drivers of estrogen receptor-positive (ER+) breast cancer risk as well as cancer progression." (PMID 34712617, 2021). "In MCF7 cells, L1 transposons were found to be bound by a total of 99 TFs, including ESR1, MYC, FOXA1 and E2F1, which have well-established and critical roles in cell growth and division and have been linked to breast cancer development." (PMID 34070697, 2021). "Broadly, FOXA1 facilitates proliferation and differentiation of luminal breast cancer cells through modulation of NR function." (PMID 34680352, 2021). "High FOXA1 levels have been observed in tumors with poor prognoses and in breast cancer metastases, where FOXA1 overexpression reprograms the ER binding landscape." (PMID 32235312, 2020). "The function of AR in breast cancer is also dependent upon FOXA1, as silencing of FOXA1 inhibits AR binding of target DNA as well as cell growth." (PMID 33062889, 2020). "On the other hand, FoxA1 was reported to act as oncogene in acute myeloid leukemia, breast cancer, prostate cancer, esophageal adenocarcinoma, and lung adenocarcinomas." (PMID 32151057, 2020). "We apply GVITamIN on a breast cancer cohort and identify well-known cancer-related transcription factors, such as CTCF, LEF1, and FOXA1, as TFs dysregulated by breast cancer-associated SNPs." (PMID 32850701, 2020). "In particular, ER transcriptional activity in breast cancer is dependent on its binding to forkhead box A1 (FOXA1)." (PMID 33171657, 2020). "FoxA1 protein expression was increased in relation to the activation of estrogen/androgen receptors in breast cancer cell progression." (PMID 32151057, 2020). "Having been described previously to play a role in bladder cancer, in terms of the ability to drive a luminal subtype, FOXA1 has also been shown to be involved in other cancers, particularly breast cancer, where it has been shown to be a prognostic factor." (PMID 32374509, 2020). "Down-regulation of luminal breast cancer marker (Foxa1) and up-regulation of basal-like breast cancer markers (integrin α5 and integrin β1) were regulated by TWIST1 to promote breast cancer progression." (PMID 32248791, 2020). "Three of these genes belonged to the PAM50 set: AR, FOXA1, and GPR160, while the remaining genes had all been individually associated with breast cancer subtypes." (PMID 32605588, 2020). "A phenotype switch from basal-like to luminal breast cancer can be achieved through the expression of FOXA1, GATA3 or ESR111–13." (PMID 32801338, 2020). "The frequency of the promoter mutation is apparently higher in our EMPD cohort (21%) than in breast cancer (<1%), suggesting the importance of FOXA1 upregulation in EMPD." (PMID 32235312, 2020). "Conversely, NCS‐1 expression is negatively correlated to FOXA1, ESR1, and PGR, which are more commonly associated with the breast cancer luminal subtype." (PMID 31647602, 2020). "The genomic distribution of FOXA1/ER binding sites is significantly altered in endocrine resistant cell lines and poor-prognosis breast cancers." (PMID 31895944, 2020). "The concurrent expression of GATA3, NR2F2, and FOXA1 in ERα positive breast carcinomas is intriguing." (PMID 31588232, 2019). "Several direct downstream targets of GATA3 in the luminal epithelium have been identified including FOXA1, a key regulator of ER binding in the breast cancer cells." (PMID 31408468, 2019). "High FOXA1 expression and low FOXA1 DNA methylation in the ER+ subtype of breast cancer are potential indicators of favorable prognosis." (PMID 31562808, 2019).
breast carcinoma (continued). "In this present study, FOXA1 and Nestin expression were examined using immunohistochemistry for 164 breast cancer metastases, followed by Cox regression analysis to assess their prognostic significance in breast cancer." (PMID 30819139, 2019). "Overall, the identification of a KDM3A/KDM4B co-regulatory axis that regulates FOXA1 and subsequent ER deposition on chromatin in breast cancer enhances the understanding of the mechanisms controlling ER-transcriptional activity." (PMID 31390833, 2019). "FOXA1 was a significant predictor of favorable outcome in primary breast cancer, while Nestin expression is preferentially found in triple-negative tumors with increased rate of nodal metastases, and reduced survival." (PMID 30819139, 2019). "In future studies, it would be interesting to investigate FOXA1 and Nestin expression in the primary breast carcinoma corresponding to the 164 metastatic breast carcinomas investigated here." (PMID 30819139, 2019). "The prognostic cutoff for FOXA1 used in breast cancer varies considerably, reaching 71% for hormone receptor-positive breast cancers." (PMID 31888566, 2019). "Our findings also support the notion that FOXA1 is not only involved in ER binding of breast cancer cells but also involved in ER binding in the normal mouse mammary gland." (PMID 31408468, 2019). "Studies have shown that FOXA1 acts as a pioneer factor for ER binding in the distal enhancer sites in breast cancer cells." (PMID 31408468, 2019). "This study investigates for the first time AR and FOXA1 expressions in a large cohort of feline invasive mammary carcinomas." (PMID 31888566, 2019). "We examined the expression profile of FOXA1 in different breast cancer (BRCA) subtypes in TCGA-BRCA using the UCSC Xena browser." (PMID 31562808, 2019). "In our transcriptome studies, the expression of forkhead box A1 (FOXA1) gene, which acts to control transcription of estrogen receptor-regulated genes and repress the basallike features of breast cancer cells, was observed only in PMC42-LA." (PMID 31430931, 2019). "FOXA1 expression has also been assessed in primary carcinomas from other anatomic sites than breast carcinoma." (PMID 30819139, 2019). "Therefore, we assume that studying the effects of early parity on some genes such as ESR1 and FOXA1, which have important functions in estrogen responsiveness, can improve the better understanding of underlying mechanisms of early pregnancy associated with breast cancer protective effect." (PMID 30054444, 2019). "To date, immunohistochemical analysis of FOXA1 and Nestin expression has only been performed using primary breast carcinomas." (PMID 30819139, 2019). "FOXA1 is a main regulator of steroid receptor function in cancer, and it regulates ER signaling in breast cancer." (PMID 31304632, 2019). "We propose the inclusion of FOXA1 and Nestin immunohistochemical evaluation in current immune panels for breast carcinoma to improve prognostication and therapy choice." (PMID 30819139, 2019). "In particular, the pioneer factor FOXA1 has been identified as a novel therapeutic target for the treatment of breast cancer, while the EZH2-ERα-GREB1 transcriptional axis has been shown to play a key role in therapeutic resistance." (PMID 31084623, 2019). "In this study, we identified the significance of FOXA1 expression in human ER+ breast cancer and demonstrated the role of DNA methylation." (PMID 31562808, 2019). "The relationship between FOXA1 expression and recurrence-free survival for 3779 patients with breast cancer was analyzed, separating ER+ (n = 2565) from ER− (n = 1214) cases." (PMID 31562808, 2019). "Reduction in FOXA1 expression contributes to cancer stem cell-like properties in Tamoxifen-resistant breast cancer cells through induction of Interleukin-6 (IL-6)." (PMID 30819139, 2019). "Then, the expression and prognostic value of FOXA1 was validated by our own breast cancer samples using RT-PCR." (PMID 31562808, 2019).